WIPF1 (WAS/WASL interacting protein family member 1)
Description:
Plays a role in the reorganization of the actin cytoskeleton. Contributes with NCK1 and GRB2 in the recruitment and activation of WASL. May participate in regulating the subcellular localization of WASL, resulting in the disassembly of stress fibers in favor of filopodia formation. Plays a role in the formation of cell ruffles (By similarity). Plays an important role in the intracellular motility of vaccinia virus by functioning as an adapter for recruiting WASL to vaccinia virus.
Synonyms: WASPIP; WIP; PRPL-2; WAS2
Tractability: Small molecule: a structure with a bound ligand is known. Antibody: the Human Protein Atlas places it where antibodies can reach. PROTAC: its protein half-life has been measured.
Gene: Protein-coding gene on chromosome 2 (174,559,563 to 174,682,916, reverse strand). Ensembl gene ENSG00000115935.
Subcellular location: Cytoplasmic vesicle; Cytoplasm, cytoskeleton; Cell projection, ruffle
Subcellular location (Human Protein Atlas): Cytosol; Plasma membrane
Pathways (Reactome):
Signal Transduction: CDC42 GTPase cycle; RAC1 GTPase cycle; RHO GTPases Activate WASPs and WAVEs
Disease: FCGR3A-mediated phagocytosis
Immune System: Regulation of actin dynamics for phagocytic cup formation
Gene Ontology:
Molecular function: cytoskeletal anchor activity; protein binding; protein folding chaperone; SH3 domain binding; actin binding; profilin binding
Biological process: actin filament-based movement; actin polymerization or depolymerization; protein-containing complex assembly; actin filament-based process; protein folding
Cellular component: actin cytoskeleton; actin filament; cytosol; cytoplasmic vesicle; cytoskeleton; ruffle
Genetic constraint (gnomAD): Loss-of-function variants: 13 observed, 36.56 expected, observed/expected ratio (o/e) 0.36, 90% interval 0.23 to 0.56. The upper end of that interval is the gene's LOEUF score, 0.56, which puts it in group 2 of 6, group 1 being the genes least tolerant of losing a copy. Missense variants: 591 observed, 691.34 expected, observed/expected ratio (o/e) 0.85, 90% interval 0.8 to 0.92. Synonymous variants: 265 observed, 278.89 expected, observed/expected ratio (o/e) 0.95, 90% interval 0.86 to 1.05.
Gene-disease validity (ClinGen):
ClinGen rates the evidence that WIPF1 causes each of these diseases.
Wiskott-Aldrich syndrome 2 (autosomal recessive): Definitive.
Homologues: Orthologues: dog WIPF1 (88% identical), mouse Wipf1 (88% identical), macaque WIPF1 (87% identical), rat Wipf1 (77% identical), tropical clawed frog wipf1 (64% identical), zebrafish wipf1a (48% identical), Drosophila melanogaster Vrp1 (28% identical), Caenorhabditis elegans wip-1 (24% identical). Paralogues in human: WIPF2 (39% identical), WIPF3 (30% identical).
Diseases named in the same sentence as WIPF1 in open-access papers:
WIPF1 is named in the same sentence as 61 diseases in open-access papers, as found by Europe PMC text mining. Sharing a sentence is not in itself a finding about the gene and the disease. The quoted sentences say what the papers report.
breast carcinoma (16 papers, 2015 to 2025). "Interestingly, lower WIPF1 expression was shown to be associated with better prognosis of colorectal cancer, breast cancer, and glioma." (PMID 27863429, 2017). "Importantly, high expression of WIPF1 is associated with poor prognosis in breast cancer." (PMID 28341962, 2017). "Previous studies highlighted its potential role in cancer, where WIPF1 expression levels correlated with increased cell invasion and migration in breast cancer cell lines." (PMID 40821124, 2025). "Aberrant expression of WIPF1 facilitated the invasiveness of several malignancies, such as breast cancer, colorectal cancer, and glioma, by enhancing podosome formation." (PMID 40821124, 2025). "WIPF1 was found to be a oncogene in colorectal cancer, glioma and breast cancer." (PMID 35334492, 2022). "WIPF1 knockdown inhibits the growth of glioblastoma tumor cells and breast cancer cells in vivo." (PMID 34257533, 2021). "A recent study reported that WIPF1 played a role in the matrix invasion by breast cancer cells." (PMID 27863429, 2017). "For instance, miR-200 was shown to target cytoskeleton remodeling proteins in breast cancer cells, including WASF3, Moesin, FHOD1, PPM1F, WIPF1 and Cofilin2, functional mediators of miR-200 in the suppression of invasion and/or metastasis." (PMID 26334393, 2015).
Wiskott-Aldrich syndrome (12 papers, 2006 to 2025). Wiskott-Aldrich syndrome (WAS) is a primary immunodeficiency disease characterized by microthrombocytopenia, eczema, infections and an increased risk for autoimmune manifestations and malignancies. "WIPF1 binds to a region of Wiskott-Aldrich syndrome protein (WASP) that is frequently mutated in Wiskott-Aldrich syndrome (WAS)." (PMID 30041660, 2018).
immunodeficiencies (9 papers, 2012 to 2021). "Notably, mutations in WAS, WIPF1 or DOCK8 have been reported in human immunodeficiencies, underscoring the importance of these cytoskeleton regulators during immune responses." (PMID 29337666, 2018).
eczema (7 papers, 2012 to 2023). "A female patient bearing a mutation containing a stop codon in the WIPF1 gene, which encodes WIP, displayed recurrent infections, eczema, thrombocytopenia, defective T cell proliferation and chemotaxis, and impaired NK cell effector function." (PMID 33598461, 2021). "The first primary immunodeficiency with WIP deficiency due to homozygous mutation of WIPF1 gene was described in a female child presenting with clinical picture similar to WAS including recurrent infections, thrombocytopenia, eczema, and defective T cell proliferation and chemotaxis." (PMID 36756122, 2023).
Thrombocytopenia (7 papers, 2012 to 2025). A reduction in the number of circulating thrombocytes. "Thrombocytopenia was observed in all 31 children enrolled in the study, including those with a confirmed molecular diagnosis of WAS/XLT (22 patients) and those with negative WAS gene and WIPF1 gene sequencing results (9 patients)." (PMID 40821842, 2025).
colorectal cancer (6 papers, 2017 to 2025). A primary or metastatic malignant neoplasm that affects the colon or rectum. "It has been experimentally demonstrated that WIPF1 is an oncogene in breast cancer, glioma, and colorectal cancer." (PMID 32725768, 2020). "Lowly expressed WIPF1 in colorectal cancer patients indicates a better prognosis." (PMID 32725768, 2020).
gastric cancer (3 papers, 2020 to 2024). A primary or metastatic malignant neoplasm involving the stomach. "WIPF1 regulated tumor development through the PI3K/AKT pathway and was involved in immune responses in gastric cancer." (PMID 39720726, 2024). "HCG18 can increase the expression levels of WIPF1 and DNAJB12 and activate the PI3K/AKT axis in gastric cancer cells, thus promoting gastric cancer progression." (PMID 34976998, 2021).
leukemia (3 papers, 2017 to 2021). A malignant (clonal) hematologic disorder, involving hematopoietic stem cells and characterized by the presence of primitive or atypical myeloid or lymphoid cells in the bone marrow and the blood. "Mutations in the WIPF1 binding site of WASP or in WIPF1 itself cause Wiskott-Aldrich syndrome (WAS), which predisposes people to cancer, such as leukemia and lymphoma." (PMID 27863429, 2017).
lung carcinoma (3 papers, 2020 to 2021). "However, WIPF1 was differentially expressed in smokers with lung carcinoma and might therefore be related to smoking-induced changes, which are a shared risk factor for periodontitis and VTE." (PMID 34925639, 2021). "Interestingly, WIPF1 was found as a downstream target of ETS1 in lung cancer." (PMID 34245091, 2021). "Interestingly, WIPF1 could be regulated by ETS1 in lung cancer." (PMID 34245091, 2021).
lymphoma (3 papers, 2019 to 2021). A malignant (clonal) proliferation of B- lymphocytes or T- lymphocytes which involves the lymph nodes, bone marrow and/or extranodal sites. "WASP has been linked to Wiskott–Aldrich syndrome, a recessive disease in which the WASP-homology domain is often mutated causing WASP destabilization, dissociation from WAS/WASL-interacting protein family member 1 (WIP) and lymphoma predisposition." (PMID 33928032, 2021).
pancreatic ductal adenocarcinoma (3 papers, 2018 to 2021). An infiltrating adenocarcinoma that arises from the epithelial cells of the pancreas. "According to previous studies, WIPF1 can enhance the stability of YAP/TAZ to stimulate the growth of tumor in pancreatic ductal adenocarcinoma." (PMID 32725768, 2020). "However, the role of WIPF1 in human pancreatic ductal adenocarcinoma (PDAC) remains poorly understood." (PMID 30041660, 2018).
papillary thyroid cancer (3 papers, 2017 to 2021). "It was found up‐regulated WIPF1 played a key role in BRAF V600E‐promoted papillary thyroid cancer aggressiveness." (PMID 34245091, 2021). "The overexpression of WIPF1, a key member of WIP family, can promote the IVS of papillary thyroid carcinoma cells." (PMID 32725768, 2020).
thyroid cancer (3 papers, 2017 to 2022). "Our analysis of thyroid cancer data in the TCGA database revealed a significant inverse association between the expression of WIPF1 and its methylation (r=−0.75, P=5.89E-13), suggesting that WIPF1 was epigenetically regulated." (PMID 27863429, 2017). "This represents a novel mechanism in BRAF V600E-promoted PTC aggressiveness and identifies WIPF1 as a novel therapeutic target for thyroid cancer." (PMID 27863429, 2017). "Knockdown of WIPF1 robustly inhibited anchorage-independent colony formation, migration, and invasion of thyroid cancer cells and suppressed xenograft thyroid cancer tumor growth and vascular invasion, mimicking the effects of BRAF knockdown." (PMID 27863429, 2017). "We next investigated the oncogenic property of WIPF1 in thyroid cancer cells using soft agar colony formation assay." (PMID 27863429, 2017). "In the present study, we investigated this novel mechanism and the potential of WIPF1 being a novel therapeutic target in thyroid cancer." (PMID 27863429, 2017). "We previously demonstrated that the MAPK pathway was linked to alterations in promoter methylation of certain genes in thyroid cancer cells, among which was prominently the WIPF1 gene." (PMID 27863429, 2017). "To further investigate the role of WIPF1 in thyroid cancer, we examined the relationship between WIPF1 expression and clinicopathological outcomes of PTC in the TCGA database." (PMID 27863429, 2017). "It is interesting to note that the expression of WIPF1 was the highest in TCPTC among the three PTC variants in the TCGA data analysis, again consistent with a role of WIPF1 in the development of aggressiveness of thyroid cancer." (PMID 27863429, 2017). "These functions of WIPF1 may explain its important role in thyroid cancer cell migration and invasion observed in the present study." (PMID 27863429, 2017). "In summary, the present study identifies the WIPF1 gene as having novel oncogenic functions and playing an important role in the invasiveness and aggressiveness of thyroid cancer when aberrantly up-regulated by the BRAF V600E/MAPK pathway through its promoter demethylation." (PMID 27863429, 2017). "Indeed, through a variety of in vitro studies, we demonstrated a robust role of WIPF1 in the migration and invasion as well as the sustainment of oncogenic properties (i.e., anchorage-independent growth) of thyroid cancer cells." (PMID 27863429, 2017). "The data in the present study are consistent with a model in which BRAF V600E-activated MAPK pathway causes hypomethylation of the WIPF1 promoter, hence resulting in over-expression of WIPF1, which in turn promotes the invasiveness and aggressiveness of thyroid cancer." (PMID 27863429, 2017). "Thus, when aberrantly up-regulated, WIPF1 possesses a robust oncogenic function in thyroid cancer." (PMID 27863429, 2017). "We demonstrated that anchorage-independent cell colony formation of thyroid cancer cells K1, OCUT1 and FTC133 on soft agar was all dramatically decreased with WIPF1 knockdown." (PMID 27863429, 2017). "To investigate the role of WIPF1 in thyroid cancer cellular functions, we generated stable K1, OCUT1 and FTC133 cell lines with WIPF1 knockdown using an RNA interference system mediated by a lentivirus vector." (PMID 27863429, 2017). "Interestingly, vascular invasion disappeared in tumors with WIPF1 knockdown as in tumors with BRAF V600E knockdown, providing functionally in vivo evidence for a role of WIPF1 in the invasiveness of thyroid cancer." (PMID 27863429, 2017). "In thyroid cancer cell lines with wild-type BRAF, WIPF1 expression was robustly upregulated upon introduced expression of BRAF V600E (P=0.03) whereas the opposite was seen upon BRAF knockdown or treatment with BRAF V600E or MEK inhibitors in cells harboring BRAF V600E." (PMID 27863429, 2017).
thyroid cancer (continued). "We did not observe a role of WIPF1 in thyroid cancer cell proliferation, suggesting that WIPF1 plays a role in thyroid cancer pathogenesis mainly through its function in promoting cancer cell invasion and tumor aggressiveness." (PMID 27863429, 2017).
epilepsy (2 papers, 2023 to 2025). A brain disorder characterized by episodes of abnormally increased neuronal discharge resulting in transient episodes of sensory or motor neurological dysfunction, or psychic dysfunction. "We identified five significant genes (WIPF1, IQSEC1, JAM2, ICAM3, and ZNF143) that had causal relationships with epilepsy." (PMID 37246165, 2023).
Hypertension (2 papers, 2021 to 2024). The presence of chronic increased pressure in the systemic arterial system. "Two of the recurrent AF genes also code for functions directly or indirectly linked to AF (CASQ2 and GOSR2), and some genes indicate a possible indirect link related to comorbidities, e.g., hypertension or malignancy (PPFIA4, USP34, WIPF1, SPATS2L, CAND2, and AOPEP)." (PMID 38725839, 2024).
melanoma (2 papers, 2021 to 2025). A malignant, usually aggressive tumor composed of atypical, neoplastic melanocytes. "In this study, 7 genes (CYTL1, CCL8, FCGR2C, OAS1, HAPLN3, WIPF1, CLIC2) were identified as prognostic signatures for melanoma." (PMID 33428606, 2021).
osteonecrosis (2 papers, 2025). A none disease characterized by death of bone tissue due to a lack of blood supply. "Another GWAS in a multiancestral cohort of children and adults with SLE (71/940 with osteonecrosis) identified an intronic variant in WIPF1 (WAS/WASL interacting protein family member 1) to be associated with increased osteonecrosis risk that remained after accounting for corticosteroid exposure." (PMID 39660463, 2025). "A recent GWAS in a multi-ancestral cohort of juvenile-onset and adult SLE patients (N = 940 total; N = 71 osteonecrosis) established links between an intronic variant in WIPF1 (WAS/WASL interacting protein family member 1) and increased osteonecrosis risk independent of glucocorticoid exposure." (PMID 41410901, 2025).
Stroke (2 papers, 2012 to 2020). Sudden impairment of blood flow to a part of the brain due to occlusion or rupture of an artery to the brain. "A number of new stroke-genes related to T- and dendritic cell activation and differentiation including Cd 8a, Tmem176b, Unc93b1, Vamp8, and Wipf1 also displayed persistent upregulation." (PMID 23251410, 2012). "Other identified genes previously reported in GWAS to be associated with CVD-related traits were ELL2 (GWAS of BP, insulin and glucose), TRPS1 (GWAS of BP), PID1 (GWAS of stroke, lung function and chronic obstructive pulmonary disease) and WIPF1 (GWAS of resting heart rate)." (PMID 31999706, 2020).
amyloidosis (1 paper, 2021). A disorder characterized by the localized or diffuse accumulation of amyloid protein in various anatomic sites. "The MMSE‐correlated DEPs were mainly involved in amyloidosis (DNM1, UBR1, OPTN, FERMT2), CNS disorder (WIPF1) and energy metabolism (COA6, COX7C, PDPR) processes." (PMID 34528736, 2021).
brain cancer (1 paper, 2021). A primary or metastatic malignant neoplasm affecting the brain. "It is also involved in the activation of CRC PTEN was identified as a tumor suppressor and therapeutic target for cancer WIPF1 is a candidate prognostic marker for BC, brain cancer, and CRC ErbB4 gene plays a significant role in BC prognostics and therapy." (PMID 34575665, 2021).
colon cancer (1 paper, 2020). "Our results support a hypothesis that transgelin interacts with PARP1 and regulates the expression of downstream key genes (CALM1, MYO1F, NCKIPSD, PLK4, RAC1, WAS and WIPF1), which are mainly involved in the Rho signaling pathway in the human RKO colon cancer cells." (PMID 32774160, 2020).
pancreatic cancer (1 paper, 2018). "We examined 37 individual human pancreatic cancer tissues and found that the expression of miR-141 inversely correlated with the expression of WIPF1 mRNA (r = − 0.734, p < 0.001)." (PMID 30041660, 2018). "To determine the impact of WIPF1 expression on the survival of patients with pancreatic cancer, we identified 177 PDAC cases from the TCGA database and examined the correlation between the level of expression of WIPF1 and overall survival (OS)." (PMID 30041660, 2018). "We also examined 10 paired pancreatic cancer tissues and the surrounding non-cancerous tissues and found that mRNA expression of WIPF1 was highly elevated in the PDAC tissues compared to the surrounding non-cancerous tissues (P = 0.005)." (PMID 30041660, 2018).
periodontitis (1 paper, 2021). An acute or chronic inflammatory process that affects the tissues that surround and support the teeth. "Four potential biomarker crosstalk genes were also immune genes, i.e., LGALS1, LSP1, SAMSN1, and WIPF1 between periodontitis and VTE." (PMID 34925639, 2021). "Four biomarker crosstalk genes between periodontitis and VTE were also immune genes, i.e., LGALS1, LSP1, SAMSN1, and WIPF1." (PMID 34925639, 2021). "No studies reported on a potential role of WIPF1 in periodontitis or VTE." (PMID 34925639, 2021).
spontaneous abortion (1 paper, 2025). Expulsion of the product of FERTILIZATION before completing the term of GESTATION and without deliberate interference. "In this study, we aimed to determine the role of WIPF1 in EVT invasion and assess the level of WIPF1 in the placental villi of recurrent spontaneous abortion (RSA) patients." (PMID 40821124, 2025).
cancer (21 papers, 2012 to 2025). A tumor composed of atypical neoplastic, often pleomorphic cells that invade other tissues. "Aberrant expression of WIPF1 has been reported in several cancers, contributing to invasive and metastatic properties." (PMID 34445271, 2021). "This discrepancy may be due to differences between cancer cells and trophoblast cells, or it could suggest that WIPF1 may independently regulate podosome-mediated matrix degradation." (PMID 40821124, 2025). "Since the migration and invasion of EVTs into the decidua share similarities with the invasion of host tissues by cancer cells, it could be hypothesized that WIPF1 could promote EVT migration and invasion." (PMID 40821124, 2025). "Besides, in a recent research, RhoA was found as a downstream target of WIPF1, an oncogene in many cancers." (PMID 34245091, 2021). "Besides, we also found RhoA was a downstream target of WIPF1, which was also observed in a previous research in cancer." (PMID 34245091, 2021). "WIP is known as WIPF1 (WASP-interacting protein family member 1), which has been reported to form WIP/WASp complex for immune response and take part in cancer invasion and metastasis." (PMID 32632098, 2020).